CCL21 (C-C motif chemokine ligand 21)
Diseases named in the same sentence as CCL21 in open-access papers (continued):
Sharing a sentence is not in itself a finding about the gene and the disease.
endometrial tumors (1 paper, 2019). "All together, we showed that both cytokine and chemokine production in the endometrial tumors may participate to the alteration of NK cell function, as IL-6 and IL-1β are increased in the tumor, and recruitment, as chemoattractants CCL27, CXCL12, and CCL21 are significantly reduced in the tumor." (PMID 31105699, 2019).
esophageal cancer (1 paper, 2018). A primary or metastatic malignant neoplasm involving the esophagus. "For instance, the C–C chemokine receptor type 7 (CCR7), located mainly on the membrane of mature dendritic and T cells, is capable of interacting with its specific ligand CCL21 to facilitate lymph node metastasis in esophageal cancer." (PMID 29599774, 2018).
fibrosis (1 paper, 2024). the formation of excess fibrous connective tissue in an organ or tissue in a reparative or reactive process. "In our study, eight cytokines (CCL21, a T-cell chemoattractant, IL-9, IL-17F, IL-21, IL-28A, I-309, MIP-1β, and TARC) significantly correlated with BDG exposure in those without fibrosis, while only two cytokines (eotaxin-3 and M-CSF) were correlated in those with fibrosis." (PMID 39502781, 2024).
gallbladder cancer (1 paper, 2021). "A previous study showed that poor differentiation was associated with larger tumor size in patients with CCL21-positive gallbladder cancer." (PMID 34421979, 2021).
glomerulosclerosis (1 paper, 2021). A hardening of the kidney glomerulus caused by scarring of the blood vessels. "The chemokine CCL21 secreted by podocytes interacts with CCR7 on mesangial cells to regulate mesangial cell proliferation and migration, and podocyte-derived PDGF similarly mediates mesangial cell proliferation and glomerulosclerosis." (PMID 34369383, 2021).
Hashimoto thyroiditis (1 paper, 2025). An autoimmune disorder caused by the production of autoantibodies against thyroid tissue. "Univariate binary logistic regression analysis showed that elevated serum CCL21 [OR = 2.944, 95% CI (1.464, 5.919), p=0.002] was significantly associated with Hashimoto’s thyroiditis." (PMID 41234223, 2025). "Univariate results showed that TSH, FT3, TgAb, TPOAb, and CCL21 were significantly associated with the risk of developing Hashimoto’s thyroiditis (P < 0.05)." (PMID 41234223, 2025). "We hypothesized that in patients with Hashimoto’s thyroiditis who are overweight or obese, this superimposed inflammation may modulate the CCL21/CCR7 axis—a signaling pathway implicated in immune cell migration and inflammatory responses." (PMID 41234223, 2025). "In the present study, we explored the associations of serum CCL21 and CCR7 levels with the risk of Hashimoto’s thyroiditis and evaluated differences in the expression of serum CCL21 and CCR7 in patients with different thyroid antibodies and thyroid function status." (PMID 41234223, 2025). "Serum CCL21 is significantly elevated in patients with Hashimoto’s thyroiditis and correlates with both TgAb and TPOAb levels, suggesting that it is closely related to Hashimoto’s thyroiditis." (PMID 41234223, 2025). "Further studies are needed to investigate the expression of CRR7 in lymphocyte subsets in patients with Hashimoto’s thyroiditis and the mechanisms and signaling pathways by which CCL21 mediates CCR7 to promote lymphocyte migration." (PMID 41234223, 2025). "Our study showed a significant positive correlation between the serum chemokine CCL21 and thyroid autoantibodies in patients with Hashimoto’s thyroiditis." (PMID 41234223, 2025). "Compared to patients with antibody levels below the 25th percentile, patients with Hashimoto’s thyroiditis with antibody levels in P25-P50, P50-P75, and above P75 ranges showed significantly elevated serum CCL21 levels." (PMID 41234223, 2025). "Our preliminary results indicated that serum CCL21 showed a significantly higher ROC value than TgAb and TPOAb for distinguishing patients with Hashimoto’s thyroiditis from healthy controls." (PMID 41234223, 2025). "Longitudinal follow-up of the study population will be conducted to explore the relationship between baseline CCL21 levels and Hashimoto’s thyroiditis progression." (PMID 41234223, 2025). "Our study showed that serum CCL21 levels were significantly elevated in the Hashimoto’s thyroiditis group compared with the control group and were positively correlated with TgAb and TPOAb." (PMID 41234223, 2025). "Further investigation is warranted to elucidate the role of the CCL21/CCR7 axis in the pathogenesis of Hashimoto’s thyroiditis and evaluate its therapeutic potential as a novel treatment target." (PMID 41234223, 2025). "The results of receiver operating characteristic curve analysis indicated that CCL21 has value for the diagnosis of Hashimoto’s thyroiditis [AUC (95% CI)=0.998 (0.996-1.000), p<0.001]." (PMID 41234223, 2025). "Furthermore, serum CCL21 levels were significantly higher in patients with Hashimoto’s thyroiditis who had elevated TgAb and TPOAb levels than in patients with Hashimoto’s thyroiditis who had elevated TgAb only or elevated TPOAb only." (PMID 41234223, 2025). "The findings disclosed that subpopulations of fibroblasts in the thyroid tissue of patients with Hashimoto’s thyroiditis expressed the chemokine CCL21 in significant quantities and that numerous CCL21+ fibroblasts were distributed in the T-cell area of the tertiary lymphoid organs of thyroid tissue." (PMID 41234223, 2025). "Comparison of thyroid function with serum CCL21, CCR7, and other clinical parameters in Hashimoto’s thyroiditis patients." (PMID 41234223, 2025). "CCL21, also referred to as secondary lymphoid tissue chemokine (SLC), was found to be significantly upregulated in the thyroid gland Hashimoto’s thyroiditis in a previous study." (PMID 41234223, 2025).
Hashimoto thyroiditis (continued). "In the future, we will continue to further investigate the roles of CCL21 and CCR7 in Hashimoto’s thyroiditis." (PMID 41234223, 2025). "Studies investigating the chemokine CCL21 and its receptor CCR7 in patients with Hashimoto’s thyroiditis are scarce in the literature." (PMID 41234223, 2025). "Our study indicated that serum CCL21 and CCR7 levels were significantly higher in patients with Hashimoto’s thyroiditis than in healthy individuals." (PMID 41234223, 2025).
head and neck carcinoma (1 paper, 2015). A carcinoma that arises from the head and neck region. "Prior studies have documented the role of phosphatidylinositol 3-kinase (PI3K) and its downstream mediator protein kinase B (AKT) in the survival and invasiveness of head and neck carcinoma cells through CCL21/CCR7 interaction." (PMID 25744065, 2015).
hepatic disease (1 paper, 2010). "Similar induction of CCL21, CXCL16, CXCL9 and CXCL13 in the liver in other models of hepatic disease suggests that common mechanisms regulate the recruitment of lymphocytes to the liver following inflammation." (PMID 20502518, 2010).
HIV-1 infection (1 paper, 2016). The type species of lentivirus and the etiologic agent of acquired immunodeficiency syndrome (AIDS). "However, our results show that levels of IL7 and CCL21 actually decrease in lymph nodes under advanced HIV-1 infection, which is consistent with our perspective that peripheral recovery of CD4+ T cells does not represent their recovery in lymph nodes." (PMID 27011165, 2016).
immune deficiency (1 paper, 2016). "CCL3 is important for T cell and monocyte trafficking and a key function of CCL21 is in T cell and DC homing to lymph nodes, which explains in part the role of deficient chemokines in the immune deficiency state of CKD stage 5." (PMID 27795695, 2016).
injury (1 paper, 2023). Damage inflicted on the body as the direct or indirect result of an external force, with or without disruption of structural continuity. "Ccl19 and Ccl21 genes are involved in modulating NF-κB pathway activation, and NF-κB signaling pathway is activated in LPS-induced lung injury animals." (PMID 37362920, 2023).
juvenile dermatomyositis (1 paper, 2019). Juvenile dermatomyositis (JDM) is the early-onset form of dermatomyositis (DM), a systemic, autoimmune inflammatory muscle disorder, characterized by proximal muscle weakness, evocative skin lesion, and systemic manifestations. "In polymyositis, blood vessels stained only faintly for PNAd and CCL21, while in juvenile dermatomyositis, in which tertiary lymphoid follicle-like structure was reported in the past, they stained positively." (PMID 31533865, 2019).
kidney damage (1 paper, 2021). "Thus, CCL21 is likely transported into EVs and participated the process of kidney damage in DN." (PMID 34404433, 2021).
Lymphadenopathy (1 paper, 2019). Enlargement (swelling) of a lymph node. "This gives partial explanation to the reduced cellular content of the lymph node and significant reduction in lymphadenopathy which was ameliorated through PMXB treatment where the CCL21 content in the lymph node is downregulated." (PMID 30972059, 2019). "PMXB treatment however did not resolve inflammation within the colon or associated mesenteric lymphatic dysfunction but did however prevent lymphadenopathy within the MLN through alteration of CCL21 gradients and CD103+ DC migration." (PMID 30972059, 2019).
lymphedema (1 paper, 2025). Excess fluid collection in tissues, causing swelling. "Additionally, at the late stages of lymphedema development, the activation of lymphatic endothelial cells through lymphatic injury may induce chemokine and cytokine production, such as CCL21, to promote the infiltration and proliferation of CD4+ T cells around the lymphatic vessels." (PMID 39941140, 2025).
mesothelioma (1 paper, 2025). A usually malignant and aggressive neoplasm of the mesothelium which is often associated with exposure to asbestos. "Significantly higher levels of multiple chemokines were expressed in R- vs NR- mesotheliomas, namely CCL5, CCL16, CCL17, CCL19, CCL21, CCL25, and CXCL14 Benajmini-Hochberg adjusted P values < 0.05." (PMID 40691143, 2025).
multiple myeloma (1 paper, 2024). "BCMA/CS1 bispecific TRuC-T cells secreting IL-7 and CCL21 may represent a novel therapy for relapsed/refractory multiple myeloma." (PMID 39776916, 2024). "Via systematic optimization, we generated BC-7×21 TRuC-T cells secreting IL-7 and CCL21 that could robustly eliminate multiple myeloma cells in vitro and in vivo." (PMID 39776916, 2024).
Myocardial fibrosis (1 paper, 2012). "CCL21 expression may thus be one of the stimuli driving myocardial fibrosis and pathological remodeling both in CCC and NIC." (PMID 23150742, 2012).
myositis (1 paper, 2018). "In large scale case-control studies in a Chinese Han population using candidate gene approach, CCL21, a myositis susceptibility gene in Caucasians, was found to associate with PM or PM-associated ILD, TNFAIP3 and IRF5 with myositis or myositis-associated ILD, and PLCL1 with DM and DM-associated ILD." (PMID 29854780, 2018).
nodular sclerosis (1 paper, 2021). "Histologically, CCL21 mRNA expression increased progressively with the deterioration of tubulointerstitial inflammation and showed the highest level in nodular sclerosis group (class III) in DN patients." (PMID 34404433, 2021). "Interestingly, patients from class III, with nodular sclerosis, showed sharply increase in CCL21 mRNA expression compared with patients from class II (mild or severe mesangial expansion) and IV (advanced diabetic glomerulosclerosis)." (PMID 34404433, 2021).
osteosarcoma (1 paper, 2023). A usually aggressive malignant bone-forming mesenchymal neoplasm, predominantly affecting adolescents and young adults. "This study provides the clinical insight that chemokine signaling pathway genes (CCL21, CCL22, CCL24, CXCL11, CXCL12, CXCL13, GNAI2, and RAC2) in proliferating cells might be the potential biomarkers for treatment of osteosarcoma." (PMID 37537613, 2023).
pancreatic adenocarcinoma (1 paper, 2022). "Sensory neurons can produce CCL21 in pancreatic adenocarcinoma to enhance cell migration in patients and orthotopic tumors in mice." (PMID 35203305, 2022). "CCR7/CCL21 activation and its role in EMT using different pancreatic adenocarcinoma cell lines and resected tissue were investigated." (PMID 35203305, 2022).
periodontitis (1 paper, 2025). An acute or chronic inflammatory process that affects the tissues that surround and support the teeth. "Notably, the expression of CCL21 in human gingival lymphatic vessels is downregulated during periodontitis, a trend also observed in mice with periodontitis." (PMID 40496852, 2025).
Peritoneal Fibrosis (1 paper, 2014). Disorder characterized by a wide range of structural changes in PERITONEUM, resulting from fibrogenic or inflammatory processes. "These are circulating fibroblast precursors that are attracted by CCL21 and may contribute to peritoneal fibrosis." (PMID 24599047, 2014).
Pleural effusion (1 paper, 2012). The presence of an excessive amount of fluid in the pleural cavity. "CCL21 was reportedly induced in the lungs and secreted within granulomatous lesions after infection with M. tuberculosis, and our finding that CCL21 expression was enhanced in tuberculous pleurisy pleural effusions is consistent with this conclusion." (PMID 23028695, 2012). "Moreover, among the examined factors, CCL1, CCL21 and IL-6 were markedly increased in pleural effusions from tuberculous pleurisy patients and the supernatants of cultured PFMCs after M.tb-specific antigen stimulation." (PMID 23028695, 2012).
pleural mesothelioma (1 paper, 2024). A neoplasm that arises from the mesothelial cells of the pleura. "To elucidate whether CD93 of human MCs also regulates antitumor immunity in lung tumor patients, we first confirmed that NCI-H2452 human pleural mesothelioma cells also expressed higher levels of Cd93 and Ccl21 mRNA than human umbilical vein endothelial cells (HUVECs)." (PMID 38250037, 2024).
pneumonia (1 paper, 2023). An acute, acute and chronic, or chronic inflammation focally or diffusely affecting the lung parenchyma, caused by an infection in one or both of the lungs (by bacteria, viruses, fungi, or mycoplasma.). "Collectively, the therapeutic effects of QKL treatment on alleviating pneumonia may be dependent on suppression of the NF-κB pathway, reduction of gene (Ccl19 and Ccl21) expression and Staphylococcus abundance." (PMID 37362920, 2023).
pneumothorax (1 paper, 2021). Abnormal presence of air in the pleural cavity. "No serious adverse events occurred related to the biopsy or Ad-CCL21-DC injection procedures in any of the 15 included patients, including hemothorax or prolonged pneumothorax." (PMID 34806054, 2021).
polyp (1 paper, 2022). A usually exophytic mass attached to the underlying tissue by a broad base or a thin stalk. "Similarly, decrease in CCL5, CCL21 and CXCL12 chemokines are related with reduced cell adhesion which could enhance invasive character for polyp." (PMID 35486660, 2022).
prion disease (1 paper, 2017). A transmissible disease that is caused by a protein that is able to induce abnormal folding of normal cellular proteins, leading to characteristic spongiform brain changes, which are associated with neuronal loss without an inflammatory response. "Consistent with the demonstrations that T cells do not influence prion disease pathogenesis, an absence of CCR7-CCL19/CCL21-signaling does not influence oral prion disease pathogenesis." (PMID 29186791, 2017).
Pruritus (1 paper, 2018). Pruritus is an itch or a sensation that makes a person want to scratch. "Overall, the only immune-mediated TRAEs observed were mild and isolated to the skin: 5.4% versus 5.6% grade 1 pruritus and 5.4% vs. 2.8% dry mouth for GM.CD40L versus GM.CD40L.CCL21." (PMID 30209589, 2018).
pulmonary tuberculosis (1 paper, 2021). A bacterial infection that affects the lungs and is caused by Mycobacterium tuberculosis. "CCR7 ligation by CCL19 and CCL21 is vital for the positioning of T cells and dendritic cells of secondary lymphoid tissues, and CCR7-deficient mice, which are deficient in CCL19 and CCL21 signaling, are fully capable to control pulmonary tuberculosis." (PMID 33686954, 2021).
renal carcinoma (1 paper, 2021). A carcinoma arising from the epithelium of the renal parenchyma or the renal pelvis. "Next, we examined the expression of CCL21 in kidney biopsy in DN patients, normal kidney tissue from patients with renal carcinoma was used as the controls." (PMID 34404433, 2021).
renal dysfunction (1 paper, 2021). "Notably, DN patients with normal eGFR (eGFR > 90 ml/min/1.73m2, n = 6) showed remarkable elevation of urinary small EVs derived CCL21 mRNA compared with T2DM patients and healthy controls, indicating the earlier enhanced secretion of small EVs derived CCL21 mRNA than renal dysfunction." (PMID 34404433, 2021).
rickettsiae infection (1 paper, 2014). "Based on their role in concerting immunological and inflammatory responses, we hypothesized that CCL19 and CCL21 may play a pathogenic role in rickettsiae infection." (PMID 24507453, 2014). "Based on their essential role in concerting immunological and inflammatory responses we hypothesized that the homeostatic chemokines CCL19 and CCL21 may play a pathogenic role in rickettsiae infection." (PMID 24507453, 2014).
sarcoma (1 paper, 2025). A usually aggressive malignant neoplasm of the soft tissue or bone. "It includes information on cytokines that have been poorly studied in sarcoma peripheral blood samples, such as IL-24, IL-27, CCL21, CXCL5, and CXCL14." (PMID 41008853, 2025). "Levels of IL-1β, IL-4, IL-6, CXCL5, CXCL12, CXCL14, MIF, IGF-1, TGFβ-1, and CCL21 were increased in one or more sarcoma cohorts compared with controls, and levels of IL-15 and IL-16 were significantly lower in one or more sarcoma cohorts compared to healthy controls." (PMID 41008853, 2025).
schistosomiasis (1 paper, 2012). An infectious disease caused by parasitic trematodes of the genus Schistosoma that colonize human blood vessels and release eggs that can cause granulomatous reactions leading to acute (swimmer's itch or acute schistosomiasis syndrome) or chronic disease. "CCL4 and CCL21 were reported in the liver of mice with schistosomiasis." (PMID 22905138, 2012).
scrub typhus (1 paper, 2014). Scrub typhus is a rare dust mite-borne infectious disease caused by the Orientia tsutsugamushi bacterium and characterized clinically by an eruptive fever which is potentially serious. "Several of the mediators were significantly raised in scrub typhus as compared with other infectious disease controls, including both CC and CXC chemokines, and some of these were also related to disease severity and mortality (e.g., MIP-1β, MCP-1, CCL21 and IL-8)." (PMID 24516677, 2014).
serous ovarian cancer (1 paper, 2022).
testicular cancer (1 paper, 2026). A primary or metastatic malignant neoplasm that affects the testis. "The testicular cancer samples were grouped by the expression patterns of Copines genes, and the DEGs between groups included GNLY, MGP1, CFD2, CCL21, SPARCL13 as well as some other genes involved in the malignant progression of cancer." (PMID 40337972, 2026).
thyroid tumor (1 paper, 2021). A benign or malignant neoplasm affecting the thyroid gland. "Indeed, CCL21 was significantly associated with lymphocyte infiltration in an RNA sequencing study using clinical samples from patients with T1N0 and T2-3N1 thyroid tumors carrying wildtype BRAF and the V600E mutation." (PMID 34522174, 2021).
transitional cell carcinoma (1 paper, 2019). A malignant neoplasm arising from the transitional epithelium, usually affecting the urinary bladder, ureter, or renal pelvis. "In another study, CCR7 knockdown by siRNA significantly abrogated the CCL21-induced migration of transitional cell carcinoma UM-UC-3 cells." (PMID 30781353, 2019).